BRCA2 (BRCA2 DNA repair associated)
Diseases named in the same sentence as BRCA2 in open-access papers (continued):
Sharing a sentence is not in itself a finding about the gene and the disease.
breast cancer (continued). "Pathogenic variants (PVs) carriers in BRCA1 or BRCA2 are associated with an elevated lifetime risk of developing breast cancer (BC) and/or ovarian cancer (OC)." (PMID 32438681, 2020). "Here we report a case involving the identification of a previously undetected pathogenic MEI in BRCA2 using an updated variant calling method in a patient with early-onset breast cancer." (PMID 32884827, 2020). "Out of the 10 979 BRCA2 mutation carriers they identified, 5605 were diagnosed with breast cancer and 2369 with ovarian cancer." (PMID 32255263, 2020). "Management ranges from altered surgical and adjuvant approaches for women with BRCA1 and BRCA2 mutations, to enhanced surveillance for women with mutations in moderate-penetrance breast cancer genes or in genes associated with risk of other types of cancer." (PMID 31963545, 2020). "We analyzed germline variants of 11 breast cancer susceptibility genes for 1,995 Japanese breast cancer patients, and identified 101 (5.1%) pathogenic variants, including 62 BRCA2 and 15 BRCA1 mutations." (PMID 33067557, 2020). "Nevertheless, Caucasian women, specifically Ashkenazi Jews who are carriers of BRCA1 and BRCA2 mutations, still have higher risk of developing breast cancer." (PMID 32183060, 2020). "After adjusting for age, the odds of a BRCA2 mutation carrier developing MF/MC breast cancer were 3.7‐fold greater than in BRCA1 mutation carriers (CI: 1.77–7.78, p = 0.001)." (PMID 32022473, 2020). "To date, several studies have utilized different types of assays to evaluate the radiosensitivity in BRCA1/BRCA2-associated breast cancer patients compared to sporadic one and healthy individuals." (PMID 33013205, 2020). "The unadjusted odds (in binary logistic regression analysis) of a breast cancer being MF/MC in BRCA2 mutation carriers was 5.8 times greater than in a BRCA1 mutation carrier who developed breast cancer (CI: 3.31–10.12) (p < 0.001)." (PMID 32022473, 2020). "Reduced expression levels of BRCA2 have been evidenced in canine mammary tumors and are caused by different reported mechanisms." (PMID 32005245, 2020). "BRCA1 and BRCA2 mutations have been found in 5–10% of all breast cancers and in up to 20–25% of tumors in patients with a family of breast and/or ovarian cancer." (PMID 33019612, 2020). "A recent meta-analysis explored the impact of BRCA1 and BRCA2 mutations on survival of ovarian and breast cancer, and claimed that these mutations should be considered when designing appropriate treatment strategies." (PMID 32096544, 2020). "The gene that contributed most to inherited breast cancer risk in this population was BRCA2, followed by BRCA1, together accounting for more than 5% of the cases." (PMID 32318955, 2020). "Pathological data was available for 702 BRCA1 and 302 BRCA2 mutation carriers in the same cohort that developed a contralateral breast cancer." (PMID 32481735, 2020). "For instance, genome-wide association studies performed by the Breast Cancer Association Consortium showed that BRCA2, CHEK2, ESR1, FGFR2, MDM4 and PIK3R3 carry germline variants associated with BC development." (PMID 32210335, 2020). "One patient with a BRCA2 germline mutation had previously underwent mastectomy for breast cancer before the diagnosis of ICC." (PMID 32631434, 2020). "In contrast to BRCA1-associated breast cancers, BRCA2-associated tumors are very similar to sporadically-occurring “luminal-type” tumors." (PMID 33117676, 2020). "Nearly 50% of all hereditary breast cancer cases are due to germline mutations in the BRCA1/BRCA2 genes and are associated with early-onset breast cancer." (PMID 33067490, 2020). "Around 10–20% of ovarian cancer (OC) and 6% breast cancer (BC) overall are caused by inheritable BRCA1/BRCA2 mutations." (PMID 32708835, 2020). "This is the first case to report constitutional mosaicism for a BRCA2 mutation and shows that BRCA2 mosaicism can underlie early-onset breast cancer." (PMID 32468491, 2020).
breast cancer (continued). "We summarized the current evidence of canine BRCA2 gene alterations and their association with mammary tumors." (PMID 32005245, 2020). "Especially mutations in the BReast CAncer genes BRCA1 and BRCA2, which are key genes for the regulation and repair of DNA, increase the risks for breast cancer to 55–60% and for ovarian cancer to 16–59% by age 70 years in women." (PMID 32532068, 2020). "Recent studies have shown that the breast cancer type 1 susceptibility protein gene (BRCA1) and breast cancer type 2 susceptibility protein gene (BRCA2) germline mutations are major causes for cancer predisposition in families with a history of breast cancer." (PMID 33180852, 2020). "In the current study, NGS‐based genetic diagnosis 14, 34, 35, 36 was used to identify a novel heterozygous missense mutation of the gene BRCA2: c.7007G>T, p.R2336L, in a Chinese breast cancer family." (PMID 31782247, 2020). "A woman’s lifetime risk of developing breast cancer is greatly increased when she inherits a BRCA1 or BRCA2 gene mutation." (PMID 31832891, 2020). "Breast cancers with BRCA1 or BRCA2 mutations are characterized by different gene expression patterns, highlighting the influence of heritable mutations on the phenotype and chemosensitivity of cancer." (PMID 32053991, 2020). "It was also found that TMB with mutations of BRCA1 or BRCA2 was a prognosis signature in breast cancer, which was able to predict the treatment response." (PMID 32729618, 2020). "BRCA2, encoding the breast cancer type 2 susceptibility protein, is responsible for repairing DNA in multiple types of cancer cells, including breast cancer." (PMID 32101536, 2020). "The most important finding of the current study is that in the 17 BRCA2 mutation carriers diagnosed with breast cancer before age 40, there was just one mammography-only lesion concerning a 6 mm DCIS grade 3 in a 38-year-old woman (5,9% (1/17))." (PMID 32333294, 2020). "The S1832P, T2766I, N2781I, and K2860T mutations in BRCA2 were found to be associated with breast cancer in the Danish population." (PMID 32356124, 2020). "Women carrying germline mutations in BRCA1 or BRCA2 are at high risk of developing breast cancer and ovarian cancer." (PMID 31948486, 2020). "Up to 12% of the cases diagnosed in young patients are hereditary tumours related to germline mutations in the breast cancer susceptibility genes BRCA1 or BRCA2." (PMID 32419845, 2020). "The unadjusted odds of breast cancer being MF/MC in BRCA2 mutation carriers were 3.2 times greater than in BRCA1 mutation carriers (CI: 1.57–6.57, p = 0.001)." (PMID 32022473, 2020). "The study included 222 BRCA1 mutation carriers, 168 of which with a history of breast cancer, and 359 BRCA2 mutation carriers, 109 with a history of breast cancer, respectively." (PMID 32140806, 2020). "The prevalence of small, deleterious mutations in BRCA1 and BRCA2 genes in men with breast cancer is well established." (PMID 32952827, 2020). "This frameshift mutation resulted in a 40% cumulative risk of developing breast cancer by age 70 (95% CI, 17–77), similar to that for BRCA2 mutation carriers (~45%; 95% CI, 31–56), implying a striking role of PALB2 in predisposition to breast cancer." (PMID 32185139, 2020). "Meanwhile, germline BRCA1 and BRCA2 mutations, as in ovarian and breast cancer, showed an increased tendency to lead to PFTC development." (PMID 32393292, 2020). "Pathogenic BRCA1 mutation carriers have a 72% lifetime risk of developing breast cancer, while the risk for BRCA2 mutation carriers is 69%." (PMID 32070378, 2020). "BRCA1 and BRCA2 are the most studied breast cancer susceptibility genes that explain a significant proportion of hereditary breast and ovarian cancers." (PMID 33240314, 2020). "Nevertheless, mutations of the BRCA2 gene in dogs can be exploited for both diagnosis and treatment of mammary tumors in canine patients and to further advance cancer treatment in veterinary oncology." (PMID 32005245, 2020).
breast cancer (continued). "When data from women who developed MF/MC breast cancer were analysed in isolation, the prevalence of oestrogen receptor positivity was 85% amongst BRCA2 mutation carriers but only 15% in BRCA1 mutation carriers." (PMID 32022473, 2020). "Germline BRCA1 and BRCA2 mutations confer an increased lifetime risk for breast cancer and ovarian cancer." (PMID 32322271, 2020). "Carriers of BRCA1 mutations have a 70–80% chance of developing breast cancer, while those carrying BRCA2 mutations have a 40–84% risk of breast cancer." (PMID 33324554, 2020). "It is estimated that around 10% of men with breast cancer have a genetic predisposition, with mutations in the BRCA2 gene being more clearly associated." (PMID 32934847, 2020). "With defective homologous recombination DNA repair, BRCA1- and BRCA2-mutated breast cancers are targets for PARPi through the exploitation of synthetic lethality." (PMID 33257598, 2020). "For example, in our study, the gene contributing most to the breast cancer risk was BRCA2 while in studies of European ancestry or African ancestry, it was BRCA1." (PMID 32318955, 2020). "Altogether, we identified a genetic modifier that protects against breast cancer in women who carry pathogenic mutations in BRCA2 (P = 0.0008) and to a lesser extent BRCA1 (P = 0.02)." (PMID 32175645, 2020). "Due to the association of BRCA1 and BRCA2 proteins with telomere maintenance, peripheral blood was collected from 40 women (31 with breast cancer) and telomere-associated gene expression levels were assessed." (PMID 33081408, 2020). "BRCA1 mutations were more common (12.2% among breast cancer cases diagnosed at age 40 or below), while mutations in the BRCA2 gene were rare (0.08% in breast cancer patients diagnosed at age 40 or below)." (PMID 32824581, 2020). "Three variants were significantly associated with breast cancer: BRCA2 c.3170_3174delAGAAA (p.Lys1057ThrfsTer8), c.3545_3546delTT (p.Phe1182Ter), and c.8537_8538delAG (p.Glu2846GlyfsTer22)." (PMID 32300229, 2020). "Two variants (BRCA1 c.3257del and c.440del) were specific in breast cancer cases, while BRCA2 c.7409dup and c.4307T>C were detected in two hepatocellular carcinoma patients and the BRCA1 c.4801A>T variant in one cervical cancer patient, respectively." (PMID 32879886, 2020). "BRCA2 mutation increases the risk of breast cancer by 45-85% and ovarian cancer by 11-23% in the women population." (PMID 33013205, 2020). "Currently, PARP inhibitors are under clinical trials for BRCA1/BRCA2-deficient breast cancer and ovarian cancer by the approach of synthetic lethal." (PMID 32711558, 2020). "BRCA1 mutation carriers develop breast and ovarian cancer at a younger age than BRCA2 mutation carriers, and BRCA2 is associated with fewer cases of breast cancer than BRCA1." (PMID 32455662, 2020). "Approximately 57% of women with an inherited BRCA1 pathogenic variant and 49% with a BRCA2 pathogenic variant develop breast cancer by 70 years of age, compared to a lifetime risk of 12.5% in women in the general population." (PMID 32518611, 2020). "Knowledge of BRCA1 and BRCA2 mutations has a significant clinical impact on the management and prevention of breast cancer." (PMID 32733560, 2020). "Four of the five previous reviews included women with BRCA1 and BRCA2 pathogenic germline gene variants, but only in the context of breast cancer risk." (PMID 32165993, 2020). "Germline heterozygous pathogenic ATM variants are associated with fivefold higher risk of breast cancer by the age of 50 years and some rare variants have been shown to have penetrance as high as the BRCA2 gene." (PMID 33086730, 2020). "A literature review of the plausible target genes indicated that similar biological functions underscored the genetic survival associations of BRCA1 and BRCA2 carrier breast cancer patients." (PMID 32964118, 2020). "Women who carry mutations in BRCA1 or BRCA2 face 60% to 80% elevated lifetime risk to develop breast cancer by the age of 80." (PMID 32053991, 2020).
breast cancer (continued). "In contrast, approximately 72% of women who inherit a pathogenic BRCA1 mutation and 69% of women who inherit a pathogenic BRCA2 mutation will develop breast cancer by the age of 80." (PMID 32620799, 2020). "We report that the hRAD52 S346X variant reduces risk of developing breast cancer in individuals carrying germline BRCA2 pathogenic variants." (PMID 32175645, 2020). "Other breast cancer susceptibility genes have recessive phenotypes associated with biallelic PVs, including Fanconi Anemia for BRCA2 and PALB2, Ataxia Telangiectasia for ATM, and Nijmegen Breakage Syndrome for NBN." (PMID 31993860, 2020). "In BRCA2 mutation carriers, the cumulative breast cancer risk to the age of 80 years according to this data is increased up to 69% and for ovarian cancer up to 17%, respectively." (PMID 32140806, 2020). "Around 10–20% of ovarian cancer and 6% breast cancer overall are caused by inheritable BRCA1/BRCA2 PVs18." (PMID 33020566, 2020). "In this study, we evaluate the pattern and prevalence of germline mutations in BRCA1 and BRCA2 among high-risk Jordanian breast cancer patients selected as per international guidelines." (PMID 32733560, 2020). "Differences in breast cancer survival among BRCA2 mutation carriers are observed among patients carrying different genotype distributions." (PMID 32882684, 2020). "Patients with germline BRCA1 and BRCA2 mutations have annual risk of 2–6% for developing contralateral breast cancer." (PMID 33204419, 2020). "In a study of 236 Ashkenazi Jewish women with breast cancer, one of three founder BRCA1/BRCA2 variants was found in 25% of early-onset breast cancer cases (diagnosed under 45 years of age) and 18.5% of women diagnosed after 45 years of age17." (PMID 32300229, 2020). "Overall, about 15% of all breast cancer cases in men are associated with mutations in the BRCA2 gene." (PMID 32952827, 2020). "Women who carry pathogenic mutations in BRCA1 and BRCA2 have a lifetime risk of developing breast cancer of up to 80%." (PMID 32175645, 2020). "To capture a high-risk population, such as women with germline BRCA1 and BRCA2 mutations, family breast cancer history, hormone therapy and smoking history, we assume an increase of breast cancer incidence by a factor of 5 over the baseline case." (PMID 32628726, 2020). "BRCA1 (Breast cancer antigen 1) or BRCA2 (Breast cancer antigen 2) mutations confer the women with a 50–80% lifetime risk of breast cancer and 16–65% lifetime risk of ovarian cancer." (PMID 33379383, 2020). "Other studies presenting screening results in proven BRCA2 mutation carriers had small numbers, varying between 2 and 25 breast cancer cases." (PMID 32333294, 2020). "Inactivation of BRCA1 or BRCA2 is associated with a pattern of genome-wide mutations known as signature 3, which is strongly associated with breast cancers." (PMID 33324554, 2020). "A meta-analysis of the cohort studies, however, found an association between use of OC and breast cancer risk in BRCA2 mutation carriers (ES = 1.85; 95% CI 1.30–2.64)." (PMID 32140806, 2020). "In the Romanian breast cancer, the 4817A>G mutation in exon 11 of the BRCA2 gene was found to change the Lys residue to Arg, which is considered to be a pathogenic mutation." (PMID 32356124, 2020). "Our data also suggest that multifocality/multicentricity is more common in BRCA2‐associated breast cancer." (PMID 32022473, 2020). "Data from 211 women with BRCA1/2 mutations (BRCA1‐91, BRCA2‐120) and breast cancer were collected including age, tumour focality, size, type, grade and receptor profile." (PMID 32022473, 2020). "Among them, CDKN2A showed a contribution to breast cancer risk that was comparable to that conferred by BRCA2, whereas RAD51C, RAD51D, BRIP1 were proven to be responsible for an increase in ovarian cancer risk." (PMID 31936873, 2020).